ALDH2 (aldehyde dehydrogenase 2 family member)
Diseases named in the same sentence as ALDH2 in open-access papers (continued):
Sharing a sentence is not in itself a finding about the gene and the disease.
hepatocellular carcinoma (36 papers, 2014 to 2026). A malignant tumor that arises from hepatocytes. "ALDH2 deficiency activates oncogenic pathways via extracellular vesicles enriched in oxidized DNA, promoting alcohol-associated hepatocellular carcinoma." (PMID 39735553, 2024). "Some findings stated that ALDH2 mutations were critical in the activation of hepatocellular carcinoma carcinogenic pathways and related to immune characteristics in HCC." (PMID 37540213, 2023). "Contrarily, ALDH2-deficient mice were more susceptible to hepatic fibrosis and hepatocellular carcinoma under treatment with CCl4 plus alcohol." (PMID 37443810, 2023). "The ALDH2 polymorphism was also reported to be linked with an increased risk of gastrointestinal cancer including gastric cancer, pancreatic cancer, hepatocellular cancer, and colorectal cancer." (PMID 35517510, 2022). "This cohort study investigates the association of heavy alcohol intake, aldehyde dehydrogenase 2 gene (ALDH2) rs671 polymorphism, and hepatitis B virus infection with hepatocellular carcinoma development and mortality in patients with cirrhosis." (PMID 35877121, 2022). "ALDH2’s expression is associated with OS in lung adenocarcinoma, hepatocellular carcinoma, and upper tract urothelial carcinoma." (PMID 33671634, 2021). "Liu J reported that ADH1B and ALDH2 SNPs were significantly associated with pathogenesis of hepatocellular carcinoma medicated through alcohol drinking." (PMID 27927211, 2016). "Although ALDH2 rs886205 is suggested to be a functional polymorphism in hepatoma cells, further functionality studies are warranted." (PMID 25337902, 2014). "In addition, the expression of ALDH2 has been found to be a potential prognostic indicator for a number of malignancies; e.g., the downregulation of ALDH2 expression was associated with poorer prognosis in hepatocellular carcinoma, melanoma, and lung adenocarcinoma." (PMID 40137171, 2025). "While ALDH2 suppresses tumor growth in melanoma, lung adenocarcinoma, and hepatocellular carcinoma, it has been shown to promote tumorigenesis in colorectal cancer." (PMID 40558540, 2025). "ALDH2 expression is down-regulated in hepatocellular carcinoma, which can be used as a tumor inhibitor, and overexpression of ALDH2 inhibits the proliferation, migration, and invasion in hepatocellular cancer." (PMID 38378847, 2024). "What is the association of heavy alcohol intake, aldehyde dehydrogenase 2 gene (ALDH2) rs671 polymorphism, and hepatitis B virus (HBV) infection with hepatocellular carcinoma (HCC) development and mortality in patients with cirrhosis?" (PMID 35877121, 2022). "In hepatocellular carcinoma, ALDH2 expression is significantly lower in tumor tissues, especially in tumors exhibited enhanced migratory capacity." (PMID 33201835, 2020). "Patients with hepatocellular carcinoma (HCC) with high ALDH2 expression have a good prognosis." (PMID 36090994, 2022). "ALDH2, ITGB2, LGALS3, CTSB, PRDX1, and CD14 were identified as multifunctional proteins that are associated with tumorigenesis, damage, cancer cell death, necrosis, fibrosis, hepatocellular carcinoma, steatosis, and inflammation." (PMID 29481576, 2018). "The regulation of ALDH2 plays a crucial role in the development and progression of alcoholic hepatocellular carcinoma (HCC) via epigenetic mechanisms." (PMID 37781509, 2023). "Patients with high ALDH2 expression in hepatocellular carcinoma have a good prognosis, and the inhibition of ALDH2 expression could enhance tumor cell proliferation, stemness and migration, resulting in poor prognosis in lung adenocarcinoma patients, which is consistent with our findings." (PMID 36925967, 2023). "The role of heavy alcohol intake, aldehyde dehydrogenase 2 gene (ALDH2) rs671 polymorphism, and hepatitis B virus (HBV) infection in hepatocellular carcinoma (HCC) development and mortality remains uncertain." (PMID 35877121, 2022).
hepatocellular carcinoma (continued). "The aim of this meta-analysis was to evaluate the association of ALDH2 rs671 and CYP2E1 rs2031920 polymorphisms with hepatocellular carcinoma (HCC) susceptibility in East Asians." (PMID 31987047, 2020). "Experimental validation confirmed the upregulation of these hub genes in clinical tissues and demonstrated that ALDH2 and AKR1C3 promote hepatoma cell migration and invasion, providing experimental evidence for their potential roles in disease progression." (PMID 42136961, 2026). "Studies show a positive correlation between ALDH2 expression and immune cell infiltration, in particular of CD3+ T cells and CD8+ T cells in the tumor microenvironment of melanoma, hepatocellular carcinoma and colon cancer." (PMID 41550766, 2026). "In patients with hepatocellular carcinoma (HCC), the expression level of ALDH2 protein in tumors is significantly lower (down-regulation) than that in normal liver tissues." (PMID 37240928, 2023). "ADH1A and aldehyde dehydrogenase 2 (ALDH2) are key regulators of alcohol metabolism, and their suppression aligns well with the gene expression profiles of hepatocellular carcinoma (HCC) and can predict HCC onset and progression." (PMID 36300097, 2022). "However, to date, little is known about ALDH2 genotypes in relation to the postoperative prognosis of hepatocellular carcinoma (HCC)." (PMID 31737110, 2019). "ALDH2 is an important tumor suppression gene in the pathogenesis of hepatocellular carcinoma, which may give us a hint that the favorable outcome of LGG patients with BICD1 downregulation is probably due to upregulation of the tumor suppression gene, ALDH2." (PMID 34439934, 2021).
breast carcinoma (34 papers, 2009 to 2025). "The ALDEFLUORTM kit used to isolate CSCs in this study has previously been shown to select cells expressing high levels of ALDH1A1, ALDH3A1, ALDH1A3 and ALDH2 isoforms, which are closely linked to breast cancer stem cells." (PMID 39768151, 2024). "Our results suggest the breast cancer risk-modifying effect of the ALDH2-rs10744777 TT genotype among carriers of the BRCA2 p.K3326* mutation." (PMID 37943872, 2023). "More importantly, this study has important implications for Asian women with breast cancer as ALDH2 rs671 is a common polymorphism in Asians." (PMID 36200595, 2023). "Among those who were homozygous for the ALDH2-rs10744777 T allele, the OR for developing breast cancer associated with the BRCA2 p.K3326* mutation was 1.72 (95% CI: 1.19–2.48, P = 0.003)." (PMID 37943872, 2023). "This study enrolled one hundred and twenty‐four patients diagnosed with breast cancer according to the pathology results, genotyped for ALDH2 single‐nucleotide polymorphisms (SNP) to explore these." (PMID 36200595, 2023). "The polymorphism of ALDH2 was independently related to elevated breast cancer risk (OR = 1.27; 95% CI 1.02–1.58)." (PMID 36310188, 2023). "The common ALDH2 variant rs671 severely aggravates DNA repair‐deficient disorder Fanconi anemia, and it is expected that breast cancer developed in BRCA1/2 mutation carriers are similarly affected." (PMID 36345163, 2023). "More importantly, as ALDH2 rs671 is a common polymorphism site in Asians, this study has important implications for Asian women with breast cancer." (PMID 36200595, 2023). "A recent population-based study indicated that rs671 polymorphism of ALDH2 increased breast cancer risk independently even after adjusting for alcohol consumption." (PMID 35657923, 2022). "We identified nine cancer cell subclusters including CD44 + / ALDH2 + /ALDH6A1 + breast cancer stem cells (BCSCs), which had a copy-number variants profile similar to that of normal breast tissue." (PMID 34611125, 2021). "After investigating 2143 breast cancer cases and 3977 controls, the polymorphism in the ALDH2 gene showed increased breast cancer risk in all genetic models." (PMID 32300124, 2020). "This study is the first to reveal an independent association between variants of the ALDH2 gene and breast cancer in Asian women with results validated from a large number of cases and controls." (PMID 32300124, 2020). "The association between ALDH2 gene variants and breast cancer was validated in independent cases and all sampled control populations." (PMID 32300124, 2020). "The association between ALDH2 polymorphism and breast cancer risk was validated in 2143 breast cancer cases and 3977 controls." (PMID 32300124, 2020). "This is the first study to demonstrate an independent association between ALDH2 gene variants and breast cancer in Asian women." (PMID 32300124, 2020). "The rs671 polymorphism of ALDH2 was independently associated with increased breast cancer risk (OR = 1.27, 95% CI = 1.02–1.58 per increment of A)." (PMID 32300124, 2020). "The associations between genetic polymorphisms in ADH1B (rs1229984) and ALDH2 (rs671), alcohol consumption, the effect of a combination of the two polymorphisms, and breast cancer risk were studied in a population of East-Asian women." (PMID 32300124, 2020). "This is the first study suggesting that variants of the ALDH2 gene (rs671) increase the risk of breast cancer independently, after adjusting for other covariates such as alcohol consumption, in Asian women, and in particular in postmenopausal women." (PMID 32300124, 2020). "There is limited evidence regarding the association between ALDH2 polymorphism and risk of breast cancer." (PMID 28253921, 2017). "Among all 9 genotype combinations, only the combination of ADH1B*1/*2 and ALDH2*2/*2 was significantly associated with a reduced risk of breast cancer, although it should be mentioned that all subjects with this genotype combination were never-drinkers." (PMID 19667493, 2009).
breast carcinoma (continued). "We conducted a case–control study to determine the impact of the interaction of the effects of alcohol consumption and polymorphisms in the alcohol-metabolizing enzymes ADH1B and ALDH2 on the risk of female breast cancer in Japan." (PMID 19667493, 2009). "In support of this hypothesis, our team recently reported the breast cancer risk modifying effect of an ALDH2 common polymorphism, rs10744777, among Polish carriers of the BRCA2 p.K3326* mutation." (PMID 37943872, 2023). "Elevated ALDH1 activity has been used as a cancer stem cell biomarker of tumor aggressiveness in the invasive front of NPC, while a lower expression of ALDH2 has been associated with poor prognoses in breast cancer, lung adenocarcinoma, and HNC squamous cell carcinomas." (PMID 34680942, 2021). "In the present study, the association between alcohol consumption and breast cancer risk stratified by ALDH2 and ADH1B polymorphism status, despite the presence of variants and alcohol intake, specifically a high dose of alcohol intake, increased the risk of breast cancer." (PMID 32300124, 2020). "In our study population, the controls belonged to a population-based cohort, presumably free of Berkson’s bias, thus indicating a better reflection of females in general, and even after adjusting for alcohol consumption, polymorphisms in the ALDH2 gene independently increased breast cancer risk." (PMID 32300124, 2020). "Considering the subgroup of women with possibly higher alcohol susceptibility, the effects of the ADH1B and ALDH2 genes on alcohol drinking behavior and breast cancer risk might require further investigation." (PMID 32300124, 2020). "Thus, if the association between alcohol drinking and breast cancer risk were real, even though modest, it would be intensified by the genetic modulation of ALDH2 and/or ADH1B, which should make it more detectable." (PMID 19667493, 2009). "Finally, the study had sufficient power to assess the impact of ALDH2 polymorphism on the risk of breast cancer." (PMID 19667493, 2009). "Thus, in the present study, we investigated the association among genetic, functionally established single nucleotide polymorphisms (SNPs) in ADH1B (rs1229984) and ALDH2 (rs671), alcohol consumption, and their combined effects and breast cancer risk in an East-Asian population." (PMID 32300124, 2020). "ALDH2 high expression can promote stem cell properties, proliferation and migration in lung cancer, breast cancer and other cancers; reduce the degree of DNA damage in cancer cells; and mediate the development of drug resistance." (PMID 40796730, 2025). "Altogether, these findings demonstrate the significance of ALDH1A1, ALDH1A3, and ALDH2 inhibition as potential therapeutic targets in breast cancer." (PMID 37686694, 2023). "In a recent study, samples from patients with breast cancer were analyzed by immunohistochemistry (IHC) and the results correlated high expression of ALDH2 to poor prognosis." (PMID 37686694, 2023). "Studies of Korean women found a significant interaction for breast cancer risk between rs2031920 (CYP2E1*5) in CYP2E1 and rs671 in ALDH2 and alcohol intake." (PMID 37308906, 2023). "Citral, which is a natural product, shows potent inhibitory activity against ALDH1A1, ALDH1A3, and ALDH2 in breast cancer cells." (PMID 36694633, 2023). "Having observed this interaction in breast cancer, we aimed to investigate the association of the BRCA2 p.K3326* mutation with ESCC risk in the context of the ALDH2 rs10744777 variant." (PMID 37943872, 2023). "More recently, the polymorphism of ALDH2 gene is reported to be a risk factor with a prognostic value for alcohol‐related cancers, including HNSCC, EC, HCC, CRC, GC, and breast cancer." (PMID 36694633, 2023). "Next, to observe the effects of the ALDH2 genotype on breast cancer initiation/development, we compared the age at clinical diagnosis in each ALDH2 subgroup." (PMID 36345163, 2023).
breast carcinoma (continued). "To confirm these data, we assessed by RT-qPCR the expression of both BRIP1 and ALDH2 in 9 breast cancer cell lines representing different breast tumor subgroups." (PMID 34454516, 2021). "To further validate this prediction, we selected a panel of breast cancer cell lines to test the vulnerability of low ALDH2 expressing cells." (PMID 34454516, 2021). "While these CD44high clusters showed a downregulation in stem cell markers ALDH1A1 and ABCG2, they did show an increase in ALDH2, a stem cell marker less common in breast cancer." (PMID 34579762, 2021). "Consistently, we found ALDH2 promoter is hypermethylated in the panel of low-ALDH2 expressing breast cancer cell lines used in this study." (PMID 34454516, 2021). "In the present study, we isolated the CD44 + /ALDH2 + /ALDH6A1 + breast cancer stem cells (BCSCs) and proved the pluripotency according to trajectory analysis and RNA-velocity." (PMID 34611125, 2021). "To observe potential genetic interactions between BRCA1/2 and ALDH2 in a real‐world setting, we set out to recruit cases of BRCA1 and BRCA2 mutation carriers from breast cancer centers in Japan, and we determined ALDH2 genotypes using the previously established Taqman PCR assay." (PMID 36345163, 2023). "Interestingly, several of the breast cancer cell lines showed promoter hypermethylation of ALDH2, suggesting an epigenetic control on the expression levels of ALDH2." (PMID 34454516, 2021). "A CD44 + / ALDH2 + /ALDH6A1 + cluster was defined as breast cancer stem cells (BCSCs)." (PMID 34611125, 2021). "In the present study, expression of ALDH2 was negatively correlated with the RFS of breast cancer patients, while the underlying mechanisms have not been clearly investigated." (PMID 33201835, 2020). "However, the association between alcohol consumption and breast cancer was more prominent in those with ADH1B His/His or those that were homozygous for the major allele in both ADH1B and ALDH2." (PMID 32300124, 2020). "Alcohol consumption increased breast cancer risk, but for cases homozygous for the major alleles of ADH1B or/and ALDH2 polymorphisms, the increment was more prominent, suggesting that this was a high-risk population for breast cancers associated with alcohol consumption." (PMID 32300124, 2020). "Our results are consistent with previous reports showing that ALDH2 could be a potential marker for breast cancer stem cells." (PMID 24498388, 2014). "No significant impact on breast cancer risk by genotype was seen with individual polymorphisms for either ADH1B or ALDH2 in the analysis controlling for matching factors only or the analysis also controlling for potential confounders." (PMID 19667493, 2009). "Despite sufficient statistical power, there was no significant impact of ADH1B and ALDH2 on the risk of breast cancer." (PMID 19667493, 2009). "Therefore, we hypothesized that the ALDH2 genotypes may impact breast cancer development in BRCA1/2 mutant carriers." (PMID 36345163, 2023). "Therefore, ALDH2 may be involved in influencing the extent of cognitive impairment in patients with breast cancer who receive chemotherapy." (PMID 36200595, 2023). "EPCAM and KRT18 were employed to label epithelial cells, whereas ALDH2, CD55, and ALDH6A1 were used to identify breast cancer stem cells." (PMID 40092692, 2025). "In a study of 623 female breast cancer patients and 1845 control subjects from East Asia, it was found that alcohol consumption increased the risk of breast cancer regardless of ADH1B and ALDH2 genotypes." (PMID 36310188, 2023). "In conclusion, our current study provides evidence for the lack of impact of the ALDH2 rs671 on breast cancer development in HBOC patients." (PMID 36345163, 2023). "While among those with CC/CT genotypes of the ALDH2 rs10744777, the carriers of the BRCA2 p.K3326* mutation did not have a higher risk of breast cancer compared to non-carriers (OR = 1.05, 95% CI: 0.73–1.51, P = 0.81)." (PMID 37943872, 2023).
breast carcinoma (continued). "For breast cancer, only three studies have investigated the role of the ALDH2 gene (rs671); however, none of them reported a significant association." (PMID 32300124, 2020). "With only three studies published to date, it may be premature to rule out the role of ALDH2*2 in the occurrence of breast cancer; however, evidence from the small number of published studies to date does not support a significant association between ALDH2*2 and breast cancer." (PMID 28253921, 2017). "Another interpretation could be that ALDH2 is not expressed in the early breast cancer tissues; however, this seems a remote possibility since ALDH2 is reported to be expressed in breast cancer stem cells." (PMID 36345163, 2023). "Alcohol consumption increased the risk of breast cancer regardless of ADH1B and ALDH2 genotypes." (PMID 32300124, 2020). "Comparing the expression between ALDH1A1 and ALDH2, stronger ALDH2 expression can be found in the tumor stem-like cells of atypical teratoid/rhabdoid tumour (TSC-AT/RT), and in both parental and stem-like tumor cells of breast cancer, prostate cancer, ovarian cancer and glioblastoma (GBM)." (PMID 29552329, 2018). "However, our data indicated that the impact of ALDH2 rs671 on cancer development in Japanese HBOC patients are marginal, and the ALDH2 variant neither prevents nor accelerates the initiation and progression of breast cancer." (PMID 36345163, 2023). "However, we noted that BRCA1 mutated cases displayed a higher incidence of triple‐negative (TN) breast cancer than in BRCA2 cases, regardless of ALDH2 genotypes." (PMID 36345163, 2023).